MEG3 (maternally expressed 3)
Diseases named in the same sentence as MEG3 in open-access papers (continued):
Sharing a sentence is not in itself a finding about the gene and the disease.
gastric cancer (continued). "LncRNA-maternally expressed 3 (lncRNA-MEG3) serves as a tumor suppressor in several cancer types, such as cervical cancer, gastric cancer, and hepatocellular carcinoma." (PMID 33435156, 2021). "It has been indicated that in gastric cancer cells, MEG3 suppressed the cell migration and invasion by down‐regulating the expression of miR‐21, whereas up‐regulated miR‐21 counteracted the suppressive effect of MEG3 on cell mobility." (PMID 33332708, 2021). "LncRNA MEG3 negatively regulates the expression of miR-665 in gastric cancer, which is followed by activation of the FAK/Src pathway." (PMID 34349799, 2021). "MiR-141 was reported to inhibit gastric cancer proliferation by interacting with MEG3 and suppressing E2F3 expression." (PMID 33981611, 2021). "Long non-coding RNAs (LncRNAs) involved in the regulation of gastric cancer pathogenesis according to their differential biological functions, for example, LncRNA MEG3 served as a tumor suppressor, while LncRNA HOXA11-AS acted as an oncogene in GC development." (PMID 32516127, 2020). "For instance, LncRNA MEG3 functions as a ceRNA to suppress gastric cancer progression through sequestering oncogenic miR-181s and up-regulating Bcl-2." (PMID 31868202, 2020). "Possibly, MEG3 can suppress gastric cancer growth by inhibiting the EMT or by reducing the stemness of gastric cancer cells, which has been reported to mediate gastric cancer progression." (PMID 33291485, 2020). "This study aimed to assess the associations of lncRNA ANRIL, H19, MALAT1, MEG3, HOTAIR single-nucleotide polymorphisms (SNPs) with gastric cancer and atrophic gastritis." (PMID 33333725, 2020). "According to our previous research results, the expression of MEG3 is decreased in gastric cancer tissues." (PMID 33119060, 2020). "This study aimed to examine associations of lncRNA ANRIL (rs17694493, rs1333045, rs1011970), H19 (rs217727), MALAT1 (rs3200401), MEG3 (rs1054000), and HOTAIR (rs17840857) polymorphisms with gastric cancer and atrophic gastritis in European population." (PMID 33333725, 2020). "Network analysis showed that ATP4B and MEG3 have the same expression trend in gastric cancer and are closely related." (PMID 31584879, 2019). "By contrast, a study in gastric cancer showed that MEG3 expression is down-regulated in tumor compared to normal tissue and that, in vitro, MEG3 suppressed cell motility, negatively regulating miR-21, a pro-EMT miRNA." (PMID 31003545, 2019). "The role of MEG3 as a tumor suppressor was shown in various cancers such as pancreatic, breast, esophageal and gastric cancer." (PMID 31627266, 2019). "Studies have shown that the expression of MEG3 is downregulated in GC tissues and can regulate the proliferation and apoptosis of gastric cancer cells by targeting the expression of miR-21." (PMID 31584879, 2019). "From the results of this study, we can see that the expression level of MEG3 in gastric cancer patients is significantly lower than that in adjacent tissues, which is consistent with the results of previous studies." (PMID 31584879, 2019). "In this paper, the differentially expressed lncRNAs and mRNAs in gastric cancer patients were analyzed by using data from the TCGA database, and MEG3 and ATP4B were significantly downregulated." (PMID 31584879, 2019). "This study aims to explore the expression and degree of methylation of lncRNA MEG3 in gastric cancer tissues and to analyze its effect on the migration and proliferation of gastric cancer patients and the mechanism by which this occurs." (PMID 31584879, 2019).
gastric cancer (continued). "At present, it has been confirmed that MEG2 can affect the occurrence of gastric cancer by targeting miR-181a-5p, and the targeting of miR-181a-5p by its family member MEG3 is also verified in this paper." (PMID 31584879, 2019). "MEG3 is upregulated in esophageal squamous cell carcinoma, colorectal cancer, hepatocellular carcinoma, and gastric cancer and, therefore, promotes tumor progression." (PMID 31619233, 2019). "The downregulation of MEG3 is related to poor prognosis and promotes cell proliferation in gastric cancer and bladder cancer." (PMID 30732558, 2019). "Though MEG3 downregulation was reported in some cases of gastric cancers, we observed overexpression of MEG3 in gastric tumors in this study." (PMID 29719612, 2018). "In this context, MEG3 levels are markedly reduced in gastric cancer tissues, and its reduction significantly correlates with TNM stage, depth of invasion and tumor size." (PMID 29721215, 2018). "MEG3 was identified as a competing endogenous RNA to regulate gastric cancer progression and ectopic expression of MEG3 in HGC-27 and MGC-803 cells was shown to inhibit cell proliferation, migration, invasion, and promote apoptosis." (PMID 27992375, 2017). "MEG3 is highly expressed in healthy individuals, but its expression is lower in gastric cancer and NSCLC patients." (PMID 27528026, 2016). "LncRNA MEG3 was also found to be capable of inhibiting gastric cancer cell proliferation, migration, and invasion by competitively binding with members of the miR-181 family such as MEG3 sequestering oncogenic miR-181a." (PMID 26978351, 2016). "Another function of MEG3 has been described in gastric cancer cells, where it shows a competing endogenous activity to miR-181a." (PMID 26992233, 2016). "In gastric cancer tissue, lncRNA MEG3 expression was decreased." (PMID 38294554, 2024). "The ability of gastric cancer cells to proliferate and metastasize may be decreased by the suppression of the lncRNA MEG3." (PMID 38294554, 2024). "miR-181a was depicted as putative MEG3 target in gastric cancer and multiple myeloma." (PMID 38704452, 2024). "Moreover, the low expression or deletion of MEG3 was associated with advanced tumor node metastasis stage and poor prognosis in non-small-cell lung cancer (NSCLC), colorectal cancer, gastric cancer, and cervical cancer." (PMID 36851033, 2023). "Studies have reported that a novel ceRNA activity of lncRNA MEG3 in human gastric cancer cells, lncRNA MEG3 inhibits the cell proliferation, migration and invasion in gastric cancer by competitively binding the miR-181 family, upregulating Bcl-2, and suppressing gastric carcinogenesis." (PMID 35913967, 2022). "Though a growing number of long noncoding RNAs (lncRNAs), including HOTAIR, MEG3, MALAT1, H19, GAPLINC, and GClnc1, have been reported to be associated with gastric cancer tumorigenesis, the role of lncRNAs in human gastric cancer and their prognostic value are still inadequately explored." (PMID 32117443, 2020). "Gastric cancers show the deregulation of several lncRNAs, including MEG3, CCAT-1 and ANRIL." (PMID 33291485, 2020). "Further stratified analysis of age and gender showed that the relationship between MEG3 rs7158663 and rs10132552 and gastric cancer susceptibility is not affected by age and gender." (PMID 33119060, 2020). "MEG3 is normally expressed in many tissues in the human body, such as placenta, adrenal gland, brain and pituitary gland, but is reduced in tumor cells such as gastric cancer, liver cancer, and lung cancer." (PMID 33119060, 2020).
gastric cancer (continued). "H19 sponges miR-223p to enhance Snail expression and EMT process in gastric cancer while combined detections of H19, MEG3 and miR-675-5p have been demonstrated to effectively distinguish gastric cancer from non-tumor samples with a specificity or sensitivity of > 85% in the clinic." (PMID 32272875, 2020). "In gastric cancer tissues, MEG3 is hypermethylated to decrease expression." (PMID 31584879, 2019). "Similar to SPRY4-IT1, MEG3 expression is up-regulated by 5-aza-CdR treatment, indicating that reduced MEG3 levels in gastric cancer cells could be partly due to hypermethylation of the IG-DMR of the MEG3 gene." (PMID 29721215, 2018). "Long noncoding RNA MEG3 could function as a competing endogenous RNA for miR-181a to regulate carcinogenesis and progression of gastric cancer." (PMID 30149689, 2018). "In gastric cancer, MEG3 increases Bcl-2 levels by sequestering miR-181-a." (PMID 29641489, 2018). "The suppression of miR-148a may contribute to the down-regulation of MEG3 in gastric cancer by modulating the activity of DNMT1." (PMID 29069869, 2017). "Maternally expressed gene 3 (MEG3) gene encodes a lncRNA whose expression is lost in an expanding list of primary human tumors and tumor cell lines, however its biological role and regulatory mechanism in gastric cancer (GC) development and progression are poorly defined." (PMID 26253106, 2015). "Being experimentally validated particular RNA-DNA interactions may contribute to understanding the mechanisms of human diseases, since, for example, MEG3 and HOTAIR are associated with various cancers (gastric cancer, hepatocellular carcinoma, cervical cancer, etc.)." (PMID 32012884, 2020). "Therefore, this study sought to investigate whether the mechanism of downregulation of MEG3 in gastric cancer is related to DNA methylation and the degree of methylation in gastric cancer patients." (PMID 31584879, 2019). "In gastric cancer cell (AGS) models, overexpression of MEG3 inhibited epithelial-mesenchymal transition (EMT) by decreasing MMP-3 and MMP-9 levels and thereby inhibiting cell migration." (PMID 36968595, 2023). "However, there is no research on MEG3 rs10132552 and the risk of gastric cancer." (PMID 33119060, 2020). "MiR-208a is capable of promoting gastric cancer progression by suppressing SFRP1 and downregulating MEG3." (PMID 30911286, 2019). "Bioinformatics analysis showed that lncRNA MEG3 and ATP4B were downregulated in gastric cancer tissues compared with normal tissues." (PMID 31584879, 2019). "Expression of miR-141 and MEG3 can abolish the expression of E2F3 and inhibit the process of gastric cancer." (PMID 30429233, 2018). "Studies also reported that deletion of the MEG3 locus usually led to more aggressive cancers and MEG3 expression level correlated with tumor grade and prognosis in meningiomas, colorectal cancer (CRC), NFPA, gastric cancer (GC) and cervical cancer." (PMID 29069869, 2017). "The top 4 predicted gastric cancer-related lncRNAs, H19, HOTAIR, MEG3, and PVT1 were confirmed by the updates of the LncRNADisease database." (PMID 28963512, 2017).
gastric cancer (continued). "The situations in gastric cancer are sketched by tumor suppressor candidate 7 (TUSC7)/miR-23b, H19/miR-141, and maternally expressed 3 (MEG3)/miR-141." (PMID 26788991, 2016). "The expression of MEG3 has been shown to be altered in many human cancers, such as non-small cell lung cancer (NSCLC), hepatocellular carcinoma, meningiomas, gastric cancer and pituitary tumors." (PMID 27832204, 2016). "Another study on gastric cancer suggested that miR-141 could play an important anti-tumor role by interacting with MEG3 and targeting E2F3 during gastric cancer pathogenesis and may be a therapeutic target." (PMID 31827401, 2019). "The exact molecular mechanism behind the differential expression of MEG3 and UCA1 could be due to ethnic difference and the etiological factors specific to Indian gastric cancer patients." (PMID 29719612, 2018). "MEG3 was down-regulated in many diseases, such as NSCLC, gastric cancer and bladder cancer." (PMID 27528026, 2016). "In addition, we added the 5-Aza + sh-MEG3 treatment group to further demonstrate that the growth of gastric cancer after DNA methylation inhibition was not significantly improved compared with the MEG3 overexpression and 5-Aza treatment groups." (PMID 31584879, 2019). "However, the involvement of MEG3 in gastric cancer has not been reported." (PMID 26253106, 2015).
hepatocellular carcinoma (71 papers, 2012 to 2025). A malignant tumor that arises from hepatocytes. "Decreased levels of MEG3 have been often linked with oncogenesis and progression of lung, bladder, kidney, and hepatocellular carcinoma." (PMID 29719612, 2018). "Notably, the lncRNAs HOTTIP, H19, HOTAIR, MALAT1, antisense Igf2r (AIR), HOXA13, GTL2 (also called MEG3) and uc002mb have been reported in association with hepatocellular carcinoma (HCC)." (PMID 26172293, 2015). "Knockdown of MEG3 promoted hepatoma cells (SMMC-7721 and BEL-7402) by activating the PI3K/AKT pathway through regulating adaptor-related protein complex 1 (AP1G1)." (PMID 36968595, 2023). "The ectopic expression of MEG3 in hepatoma cells significantly inhibited proliferation and induced apoptosis." (PMID 36851033, 2023). "It has been reported that MEG3 suppressed the PI3k/Akt pathway in hepatocellular carcinoma SMMC-7721 and BEL-7402 cells, resulting in the inhibition of cell proliferation and invasion." (PMID 36851033, 2023). "MEG3 enhances adenosine-induced hepatocellular carcinoma cytotoxicity by downregulating ILF3 and activating this signaling axis." (PMID 36523500, 2022). "For instance, miRNA-29 upregulates the expression of lncRNA MEG3 through the inhibition of DNA methyltransferase activity, resulting in a reduction of methylation of MEG3 promoter in hepatocellular cancer." (PMID 35246252, 2022). "In many cancerous tissues, such as gastric cancer, colorectal cancer, ovarian cancer, and hepatocellular carcinoma, lncRNA MEG3 has been found to be downregulated." (PMID 34421993, 2021). "Another study has indicated that MEG3 inhibits autophagy to contribute to adenosine-induced cytotoxicity in hepatoma HepG2 cells." (PMID 33602903, 2021). "Up-regulation of miR-29a elevates MEG3 expression and hinders cell growth as well as promotes cell apoptosis in hepatocellular cancer." (PMID 32493490, 2020). "The long non-coding RNA (lncRNA) maternally expressed gene 3 (MEG3), a tumor suppressor, is critical for the carcinogenesis and progression of different cancers, including hepatocellular carcinoma (HCC)." (PMID 31531526, 2019). "Dysregulation of MEG3 has been found in various human tumors, including bladder cancer, hepatocellular carcinoma, lung cancer and ovarian cancer." (PMID 30386180, 2018). "Previous studies have shown that inhibition or knockdown of DNA methyltransferase 1 (DNMT1) can restore MEG3 expression in human hepatocellular carcinoma cells and hepatic stellate cells." (PMID 27832204, 2016). "Taken together, these results demonstrated that MEG3 can inhibit the proliferation of human hepatoma cells." (PMID 26444285, 2015). "Next, to determine why MEG3 can inhibit hepatoma cell growth, cell cycle and apoptosis were analyzed by flow cytometry." (PMID 26444285, 2015). "To quantify further analysis of the functional mechanism of MEG3, we constructed SK-Hep–1 hepatoma cell lines that stably over-expressed MEG3." (PMID 26444285, 2015).